MTOR (mechanistic target of rapamycin kinase)
Diseases named in the same sentence as MTOR in open-access papers (continued):
Sharing a sentence is not in itself a finding about the gene and the disease.
tumor (continued). "HSPA12B secreted by tumor-associated endothelial cells induces M2 polarization of macrophages by activating the PI3K/Akt/mTOR signaling pathway, thus promoting the formation of the immunosuppressive microenvironment within tumors." (PMID 34712697, 2021). "We also observed that inhibition of mTOR caused tumor regression and reduced tumor vascular density in short-term experiments performed in xenograft models of MEC." (PMID 33479203, 2021). "A total of 39% of tumor associated-microglia/macrophages overexpressed phosphorylated-mTOR in human GBM tissues." (PMID 34439380, 2021). "HSF1 activation in multiple cancers is significantly associated with tumor metastasis and death and mTOR is essential for HSF1 activation and HSP90 synthesis." (PMID 33946531, 2021). "mTOR signaling pathway have been linked to insulin resistance, tumor formation and angiogenesis, T lymphocyte activation and adipogenesis." (PMID 34535145, 2021). "This case supports mTOR mutation as a mechanism of resistance, and underscores the importance of tumor molecular profiling, exemplifying precision medicine in action." (PMID 34853384, 2021). "The researchers used publicly available tumor genome sequencing data identifying 33 mTOR mutations that confer pathway hyperactivation." (PMID 34533198, 2021). "Considering the central role of mTOR in metabolic and translational reprogramming, it can affect tumor-associated immune cells to undergo phenotypic and functional reprogramming in TME." (PMID 35250965, 2021). "Loss of function mutations in TSC1 and TSC2 genes results in constitutive mTOR activation and tumor progression." (PMID 35250965, 2021). "This signalling pathway is dysregulated in many types of tumours, usually as a consequence of mutations upstream of mTOR, including activating mutations in PI3K (present in 32% of CRC), and generally associated with late stages of tumorigenesis." (PMID 34359657, 2021). "Representative signaling pathways known to be involved in tumor growth include PI3K/AKT/mTOR, and Ras/Raf/MAPK, which are associated with stimulation of proliferation and protection from apoptosis." (PMID 33861751, 2021). "Tumours in the T2 subgroup also had a higher tumour mutation burden (point mutations per Mb) (p-adj ≤ 0.03) and harboured 80% of the mutations in mTOR pathway genes." (PMID 33536587, 2021). "PTEN-deficient tumor xenografts were established in nude mice that were treated with PI3K/AKT/mTOR and/or STAT3 inhibitors." (PMID 33431808, 2021). "Sorafenib induces tumor-suppressive autophagy in the parental HCC cells but induces the phosphorylation of Akt followed by mTOR and causes protective autophagy in sorafenib-resistant HCC cells." (PMID 34829834, 2021). "The overactivation of the PI3K/Akt/mTOR pathway, a signaling pathway that plays a key role in cellular growth and survival, has been implicated in various tumor pathogeneses." (PMID 34824953, 2021). "The HER2 hyperactivity associated with this subtype drives tumor growth by up-regulation of mechanistic target of rapamycin (mTOR) pathway activity and a metabolic shift to glycolysis." (PMID 34208071, 2021). "PTEN loss activates PI3K/Akt/mTOR signaling pathway, tumor proliferation is active, and EES is decreased (decreased Ve)." (PMID 33865336, 2021). "Recurrent somatic mutations of PIK3CA increase the activity of PI3Ks and the loss of phosphatase and tension homolog (PTEN, a tumor suppressor that inhibits PI3K) also can result in the overactivation of the PI3K/AKT/mTOR pathway." (PMID 33585182, 2020). "Overexpression of GAS5 is strongly associated with the suppression of tumor growth and development, because it suppresses miRNA-106a-5p expression through the mammalian target of the rapamycin (mTOR) pathway in gastric cancer." (PMID 32354045, 2020). "Previous studies have suggested that PI3K/AKT/mTOR signaling pathway is closely associated with autophagy and functions to regulate tumor cell proliferation and apoptosis." (PMID 32903546, 2020).
tumor (continued). "For example, whereas subtype-1 tumours exhibit hyperactivation of mTOR-associated signalling, subtype-2 tumours display increased activation of SMAD4-associated signalling." (PMID 31988390, 2020). "The mTOR pathway is a key regulatory element of this metabolic adaptation, which is also linked to survival, metastasis formation, and changes in tumor microenvironment." (PMID 32709151, 2020). "The authors found that the decreased expression of vascular endothelial growth factor (VEGF) following mTOR inhibition, and the consequent antiangiogenic effects on the tumour microvasculature, was the underlying mechanism of radiosensitivity." (PMID 32443649, 2020). "PTEN (Phosphatase and TENsin homolog; 10q23.31), a tumor suppressor gene encoding a lipid phosphatase protein that negatively regulates the PI3K/AKT/mTOR signaling pathway, is the responsible gene;." (PMID 32326947, 2020). "Both the Hh and mammalian target of rapamycin (mTOR) signaling pathways are associated with angiogenesis in the tumor microenvironment." (PMID 31910904, 2020). "To elucidate the molecular mechanism underlying the anti-tumor effects of deoxyshikonin, we detected the influence of deoxyshikonin on the Akt/mTOR signaling in AML cells." (PMID 32850379, 2020). "PDX HBCx-118 (BRCA2 and AKT1 mutated) responded to the combination of AZD5363 plus fulvestrant, while PDX HBCx-142 (AKT1 and mTOR mutated) responded with tumour regression to everolimus and with stable disease to volasertib, AZD5363 and palbo + fulvestrant." (PMID 32792481, 2020). "These different data emphasise that in one hand, Ras/MAPK or PI3K/AKT/mTOR pathways can initiate prostate tumour development, and in the other hand that these pathways are implicated in late phases of tumour progression." (PMID 32385236, 2020). "Taken together, these results indicated that reduction of PD-L1 by PG2 in tumor cells was associated with downregulation AKT/mTOR/p70S6K pathway." (PMID 32308547, 2020). "Tumor suppressor TSC2 is a negative regulator upstream of mTOR and its inactivating mutations cause tuberous sclerosis complex, an autosomal dominant syndrome which results in tumor development in multiple organs." (PMID 32308763, 2020). "Comparative transcriptomic profiling of the pair of tumor cells and gene set enrichment analysis suggested mTOR pathway to be downregulated upon loss of FAK." (PMID 32493400, 2020). "The inhibition of PI3K/Akt can sensitize PTEN-deficient tumor cells to the effects of mTOR inhibition." (PMID 33344221, 2020). "(vii) The mammalian target of rapamycin (mTOR), a serine/threonine kinase multi-way implicated in carcinogenesis, has been shown to mediate tumor angiogenesis as well." (PMID 33302367, 2020). "In these two independently generated models they detected increased mTOR activity in the Tet2−/−RhoAG17V Tfh tumor cells, which underlined the equivalence of these genetic preclinical AITL models." (PMID 32796826, 2020). "Among them, AZD8055 is an inhibitor of mTORC1 and mTORC2, and it is now believed that AZD8055 has antitumor activity in acute myeloma leukemia; BEZ235 is a PI3K/mTOR inhibitor that is believed to suppress the growth of tumor cells with PI3K mutations." (PMID 33585468, 2020). "They found that ß-elemene interferes withthe PI3K/Akt/mTOR/p70S6K1 pathways and causesapoptosis in tumor cells." (PMID 31376323, 2020). "Further KEGG enrichment analysis revealed an overrepresentation involved in the key pathway linked to the tumor-promoting function such as: mTOR signaling pathway, HIF-1 signaling pathway, VEGF signaling pathway." (PMID 32226492, 2020). "Of genes previously reported as commonly mutated in PNETs, only PDGFRA and MTOR were found to be mutated in a few tumor samples, and other genes, including ATM, ATRX, TSC2, DAXX, VHL, and MEN1, were mutated only in individual samples." (PMID 32586046, 2020). "The PI3K/AKT/mTOR pathway is commonly associated with the pentraxin family in inducing tumor progression." (PMID 33013829, 2020).
tumor (continued). "In an in vivo experiment, its high expression is reported to have a direct association with elevated phosphorylation of mAKT and mTOR, implying it as an obvious cause for rapid tumor growth and aggressiveness." (PMID 33292283, 2020). "The PI3K/AKT/mTOR signaling pathway is associated with tumor cell proliferation, metabolic reprogramming, apoptosis, and metastasis." (PMID 33013829, 2020). "The dysregulation of mTOR and other proteins related to this pathway in solid tumors can cause tumor cells to be more sensitive to mTOR inhibitors than normal cells." (PMID 33396624, 2020). "Recent studies have shown that the mTOR pathway is linked to tumor development and treatment resistance." (PMID 33004943, 2020). "Herein, the mTOR cascade in both tumor cells and T cells were likely to associated with CXCL10-mediated T cells chemotaxis and anti-tumor effect." (PMID 32483450, 2020). "Within the mTOR pathway of subtype-1 tumours, we found increased expression of well-documented oncoproteins including MTOR and BRAF: both of which have previously been linked to pancreatic carcinogenesis 25–27." (PMID 31988390, 2020). "The combination therapy was synergistic and resulted in almost complete tumour growth arrest, further associating a profound role between tumorigenesis and mTOR activity." (PMID 30970654, 2019). "mTOR regulates many immune cellular functions such as differentiation, activation of T cells, tumor-associated macrophages (TAM), and antigen-presenting cells." (PMID 31766386, 2019). "Increased expression of mTOR is associated with larger, poorly differentiated and more advanced tumours." (PMID 30650598, 2019). "Deregulation of mTOR signalling can equally be induced by a loss of tumour suppressors such as PTEN, APC, and NF1." (PMID 30970654, 2019). "CSCs are a self-renewing population of cells within a tumor mass, and mTOR signaling has been implicated in regulating pancreatic CSC viability and self-renewal." (PMID 31288154, 2019). "Amongst the 101 non-synonymous point mutations identified across the different tumour regions, they reported a heterogeneous mTOR mutation which rendered the kinase constitutively active." (PMID 35582282, 2019). "In the next step, we tried to understand the deeper tumour promotor mechanism underlying the circNRIP1/miR-149-5p/AKT/mTOR axis." (PMID 30717751, 2019). "The loss of PTEN and upregulation of p-AKT and p-mTOR are linked with tumor grade, vascular invasion, intrahepatic metastasis, and matrixmetalloprotease-9 upregulation." (PMID 31450841, 2019). "Whilst the underlying molecular mechanisms as to how Src and mTOR regulate each other’s function remains to be determined, our data suggests that this targeted combination effectively reduces tumor growth and thus should be explored for the treatment of HCC." (PMID 30794695, 2019). "Perturbations in this pathway, such as oncogenic and tumor suppressor mutations that elevate mTOR signaling, lead to rewiring of metabolic pathways in ways that increase aerobic glycolysis, as Warburg reported." (PMID 31817676, 2019). "We report here that a subset of periventricular glioblastoma also exhibits an epithelioid SEGA-like appearance, and harbors mutations mapping to the MAPK/TSC/mTOR pathway, in addition to other pathogenic alterations detected in high-grade neoplasms." (PMID 31258848, 2019). "The only morphologically and mTOR-activation relevant mutation found in the tumor was in MTOR, and it was also consistent with a driver mutation." (PMID 31258848, 2019).
tumor (continued). "Aberrant PI3K/AKT pathway activation via activating PI3K mutations, amplification of genes encoding HER2, EGFR and AKT, BCR-ABL translocation or PTEN loss leads to decreased autophagy in many tumor cells largely through mTOR activation." (PMID 31438969, 2019). "Among the multiple signaling pathways that have been implicated in GBM progression, the PTEN/PI3K/Akt/mTOR axis holds center stage being involved in tumor cell growth, proliferation, and metabolism." (PMID 31387280, 2019). "Induction of autophagy in tumor cells has been found to be associated with inhibition of the PI3K/AKT/mTOR signaling pathway and such a result has been demonstrated in other types of tumors." (PMID 31920653, 2019). "AMPK is implicated in tumor development and in the regulation of protein synthesis through modulation of mTOR pathway." (PMID 31795417, 2019). "Inhibition of LAT1 causes down regulation of mTOR signaling pathway through suppressing amino acid uptake into tumor cells." (PMID 31601917, 2019). "The association of TGF-β/Smad and PI3K/Akt/mTOR signaling pathways with the molecular mechanisms of EMT in tumor cells is receiving increasing attention in research." (PMID 30609689, 2019). "In contrast, DsRed+ tumor cells were enriched for Hallmark gene sets related to mTOR, Myc, E2F, and oxidative phosphorylation signaling pathways, among others, which are known to be repressed by hypoxia." (PMID 31649238, 2019). "The PI3K/AKT/mTOR pathway is associated with tumorigenesis, metastasis, and tumor therapeutic resistance." (PMID 31929797, 2019). "Our group and others have reported that dual PI3K and mTOR inhibition is associated with strong anti-tumor activity in LMS, which was significantly greater than that of either mTOR inhibition or PI3K inhibition alone." (PMID 30683135, 2019). "Further, AKT1 and RAPGEF1 were affected by phosphorylation, and MTOR is mutated to regulate downstream proteins involved in oncogenesis and tumor invasion." (PMID 31126066, 2019). "The PI3K/AKT signalling pathway is mainly regulated through over-activation of proto-oncogenes such as AKT, subunits of PI3K and mTor through mutation and amplification, as well as loss of function of tumour suppressors such as PTEN." (PMID 31888434, 2019). "All these points closely connected with the inflammatory process associated with the higher Walker-Factor levels in these tumour-bearing rats inducing a low activity of mTOR pathway associated with an increase on inflammatory pathways." (PMID 30975087, 2019). "PTEN mutation decreases PIP3 level and overactivates the PI3/AKT/mTOR pathway, thus inhibiting apoptosis and inducing tumor development." (PMID 31450841, 2019). "Blocking lipid/cholesterol biosynthesis in AR variants-expressing CRPC cells markedly reduces tumor growth through inhibition of mTOR pathway; silencing of a fattry acid elongase, ELOVL7, also leads to regression of CRPC xenograft tumors." (PMID 31366128, 2019). "The combined targeting of SOCS5 and the PI3K/Akt/mTOR pathway provides an attractive new option for impairing tumor metastasis, which is one of the main causes underlying the dismal prognosis of HCC patients." (PMID 31406106, 2019). "It is worth to mention that the role of tumor-associated macrophages in promoting PI3K/Akt/mTOR signaling in malignant cells has been reported, which corresponds to our results regarding the role of this signaling in LL." (PMID 31552092, 2019). "The AKT/mTOR pathway is well characterized and identified to play a pathogenic role in cell proliferation, autophagy maintenance, and tumor development." (PMID 31717694, 2019). "Aberrant activation of the PI3K/Akt/mTOR pathway has been associated with cell proliferation, which is often observed in different tumor types." (PMID 31511778, 2019). "We investigated the effect of CTC on the Akt/mTOR and MAPKs signaling pathways, which are closely associated with cell proliferation and survival in tumor cell lines." (PMID 30813295, 2019).
tumor (continued). "When activated, the signal can be propagated through Akt, a downstream effector of PI3K, to mTOR, causing the phosphorylation of p70S6K, and finally leading to the rapid proliferation of tumor cells." (PMID 30609689, 2019). "Despite showing promise, rapalog monotherapy has been proven mostly insufficient in causing tumor regression, with notable exceptions of tumors showing mutations in mTOR itself, LOF mutations in TSC1 or TSC2." (PMID 30764584, 2019). "Research on inherited hamartoma syndromes has helped delineate the mTOR signalling pathway, where constitutive mTOR activation plays a pivotal role in their disease pathology and tumour predisposition." (PMID 29301334, 2018). "We show that the metastasized tumor is vulnerable to mTOR inhibition because it carries an activating MTOR mutation." (PMID 30176882, 2018). "Oncogenic PI3K–mTOR–AKT pathway reduces T-cell tumor infiltration and causes inferior outcome after PD-1 inhibition, providing a rationale for the design of combination therapies of mTOR and immune checkpoint inhibitors, as recently shown for HCC." (PMID 29662490, 2018). "These proteins can cause over-activation of mTOR pathways, leading to abnormal tumor cell proliferation." (PMID 30526568, 2018). "There is some evidence that tumours with mutations in MTOR/TSC1/2 have a better response to rapalogs, although statistical significance has not been reached." (PMID 30099580, 2018). "Microarray analysis of the expression of RNAs downstream of PI3K suggested significant activation of PI3K/AKT/mTOR pathways in this tumor, consistent with the mutations." (PMID 30062048, 2018). "In conclusion, from the nationwide cohort study of kidney transplantation in Taiwan, we found that mTOR inhibitors with exposure more than 5 years provided a protective role in reducing the risk of overall neoplasm and urothelial malignancy." (PMID 30117312, 2018). "Prior therapy, whole-exome sequencing of its extremely sensitive tumor revealed two activating mutations in mTOR." (PMID 30564554, 2018). "Data obtained from primary tumor cell cultures, only, claim that patients with high levels of mTOR activation are associated with better responses." (PMID 29938004, 2018). "By contrast, IT tumours were enriched in mutations affecting the PI3K/mTOR pathway (TSC2, PTEN), while in the MLP subtype, both chromatin remodeling and PI3K/mTOR were affected." (PMID 29321190, 2018). "Both eIF4E and 4E-BP1 and their relative abundance have been linked to tumour progression and mTOR kinase resistance." (PMID 29389967, 2018). "The importance of the PI3K/AKT/mTOR signaling pathway was reported in different cancer types and its activation is associated with advanced tumor stage and poor prognosis." (PMID 29495398, 2018). "Somatic mutations in TSC1 and TSC2 also contribute to tumor growth via unopposed mTOR signaling, and sporadic AML is similarly characterized by somatic loss-of-function alterations in TSC2." (PMID 30285856, 2018). "Activated mTOR is closely associated with tumor genesis by promoting cell proliferation and the biogenesis of macromoleculars." (PMID 29416762, 2018). "Akt/mTOR signaling activation associated with stem cell marker positivity and contributed to the selection of Epcam-positive tumor-initiating cells responsible for sorafenib resistance in HCC42,43." (PMID 29305580, 2018). "This indicates that a small population of cells in the primary tumor probably developed this particular MTOR mutation and this clonal population likely migrated and was able to seed in the lung." (PMID 30176882, 2018).